CRP (C-reactive protein)
Diseases named in the same sentence as CRP in open-access papers (continued):
Sharing a sentence is not in itself a finding about the gene and the disease.
Sepsis (continued). "Using forward stepwise modeling, the four variables that contributed most to phenotype assignment (in order of contribution) were SAPS II, medical admission, diagnosis of sepsis and basal serum CRP." (PMID 32358385, 2020). "It was found that the abnormality of the coagulation function highly suggested the occurrence of sepsis and the other parameters represented by inflammatory factors including IL-2R, IL-6, and hs-CRP had a moderate predictive value on coagulopathy." (PMID 33747973, 2020). "At present, C-reactive protein (CRP) and procalcitonin (PCT) are commonly used as biomarkers for sepsis, but their diagnostic value in bloodstream infections is still controversial." (PMID 31964768, 2020). "In our study, five different optimal cut-off levels were observed for CRP measured in the first five days of serial measurements among proven sepsis." (PMID 33233806, 2020). "This study was aimed at investigating the relationship between plasma oxidative stress factor levels and organ damage parameters such as PCT and CRP in patients with sepsis and septic shock." (PMID 32952850, 2020). "We detected much significant higher levels of PCT, CRP, and IL-6 in the proved sepsis group than the suspected neonatal sepsis cases (p ≤ 0.001, 0.001, and 0.004, respectively)." (PMID 33061986, 2020). "In comparison with the animals from the control group, those that underwent sepsis had significantly higher levels of serum CRP, TNF-α, TREM, and MDA (p < 0.05)." (PMID 32348434, 2020). "This contrast with sepsis screen where the analysis of parameters like CRP and IT ratio requires some time." (PMID 32157117, 2020). "The combination of IL-6 and CRP has recently been shown to be useful in the early diagnosis of sepsis in newborns." (PMID 33233806, 2020). "In the first one, sTREM-1, PCT, and CRP levels were measured in blood samples obtained post mortem from 16 sepsis cases and 16 non-sepsis control cases." (PMID 33092081, 2020). "The authors also looked at cases of early- and late-onset sepsis and suggested that there was a significant difference in the concentrations of IL-6 and CRP between these two groups." (PMID 32164268, 2020). "We also analyzed five other well-known sepsis markers across all available time points: procalcitonin, C-reactive protein (CRP), granulocyte colony-stimulating factor (G-CSF), IL-1β, and IL-8, as measured by a commercial bead-based immunoassay (see “Methods”)." (PMID 32451375, 2020). "Of note, CRP levels have been shown to be correlated with the outcome in several etiologies, in particular in sepsis and intracerebral hemorrhage." (PMID 33287874, 2020). "For this reason, this inverse relationship between HRG and CRP in systemic inflammatory response syndrome and sepsis cannot be expected in typical DVT patients." (PMID 32879351, 2020). "Neutrophil CD64 expression has been used as a diagnostic marker of infection and sepsis in the ICU and was found to be superior to C-reactive protein and hematological determinations for detecting systemic infection or sepsis." (PMID 32960815, 2020). "In comparing sepsis with all other diagnosis groups, CRP displayed the highest c-index and WBC the lowest." (PMID 32948801, 2020). "Twenty-seven infants were identified with proven late-onset sepsis and five infants had clinical symptoms, elevated CRP and were treated with antibiotics for seven days, but without positive blood culture." (PMID 31339925, 2019). "Second, the serum IL-26 levels were related to the severity of sepsis, including parameters such as CRP, PCT, the length of ICU stay, and SOFA score." (PMID 31464651, 2019). "CRP level increases during complex and stressful surgeries, as well as in numerous diseases, such as sepsis, decompensated heart failure, and cerebral disease." (PMID 31821367, 2019).
Sepsis (continued). "Previous studies on usefulness of C-reactive protein in malaria have only centered on the conventional CRP while those involving hs-CRP have focused on cardiovascular diseases, sepsis, HIV, and cognitive impairment." (PMID 31089391, 2019). "In high-income settings, two markers of inflammation and sepsis, C-reactive protein (CRP) and procalcitonin (PCT), are widely used to help discriminate infectious/inflammatory diseases from other conditions and to distinguish bacterial from viral infections." (PMID 31664120, 2019). "This would have yielded extra information, as this biomarkers is found superior to the CRP for the diagnosis of sepsis in most studies." (PMID 31113475, 2019). "C-reactive protein is widely used in the critical care setting, and its value as a prognostic marker is proven in many diseases including sepsis." (PMID 30717340, 2019). "CRP and PCT are the most commonly used diagnostic biomarker for pediatric sepsis and their diagnostic accuracies have been extensively studied." (PMID 31470804, 2019). "The newborns in the sepsis group had significantly higher CRP levels (p=0.001) and significantly lower platelet counts (p=0.04) (Table-I)." (PMID 31086526, 2019). "The aim of the present study was to evaluate the dynamics of IL-6, PCT and CRP in a large population of adult patients with sepsis regarding their timely prediction of success of antibiotic therapy and survival." (PMID 30760225, 2019). "Reports in which IL-6 was a better diagnostic marker for sepsis than PCT, presepsin, and CRP are consistent with our study." (PMID 31718563, 2019). "Postmortem elevated CRP levels in serum and pericardial fluid have been evaluated in pre-autopsy screening for sepsis or ketoacidosis." (PMID 31661804, 2019). "In line with these previous studies, we discovered that high expression of lncRNA ITSN1‐2 was associated with increased APACHE II score, CRP, TNF‐α, IL‐6, and IL‐8 levels in sepsis patients." (PMID 30803045, 2019). "Several clinical studies showed that PCT has higher diagnostic accuracy than CRP in the differentiation of sepsis and SIRS (PCT: AUC = 0.71–0.99; CRP: AUC = 0.54–0.65)." (PMID 31470804, 2019). "The current study monitors CRP in patients presenting with sepsis and attempts to prove that it is one of the most reliable tests in determining the resolution and predicting the outcome." (PMID 31065202, 2019). "Third, CRP showed significantly higher concentrations in septic shock patients than sepsis patients." (PMID 31309103, 2019). "Due to the excessive rise in CRP levels during an acute inflammation, this biomarker is used to indicate the presence of significant inflammatory or infectious disease, notably for sepsis." (PMID 33117982, 2019). "Inflammatory markers, such as WCC and CRP, are useful to determine the likely presence of sepsis, either locally or systemically." (PMID 31095593, 2019). "The platform’s ability to detect both PCT, an early marker and CRP, a late onset biomarker of sepsis can help to determine the severity of infection and aid physicians in monitoring a patient’s response to treatment." (PMID 33117982, 2019). "C-reactive protein (CRP) is a powerful biomarker for inflammation, infection and sepsis, and is widely used in both human and veterinary medicine." (PMID 31262326, 2019). "CRP is an acute-phase protein, and the CRP level is widely used as a marker of infectious disease and sepsis." (PMID 31215423, 2019). "The relatively slow dynamics of PCT and CRP in sepsis is a relevant issue in the intensive care management of patients." (PMID 30760225, 2019). "In summary, good survival in sepsis is predicted better by a good coagulatory state than by the inflammatory situation reflected by C-reactive protein levels." (PMID 31275752, 2019).
Sepsis (continued). "C-reactive protein is also one of the most widely studied human sepsis biomarkers, although evidence suggests that it is more useful for predicting fatal progression of septic patients rather than aiding in initial sepsis diagnosis." (PMID 30931316, 2019). "This study showed that CRP was similar in patients with sepsis and septic shock that developed within the first 24 h following admission to the ICU." (PMID 31648506, 2019). "CRP synthesis is promoted in the liver, and it is the protein most commonly used as an inflammatory indicator in sepsis and similar conditions." (PMID 31568522, 2019). "IL-1Ra was also a good predictor of clinical outcomes in cases of febrile neutropenia because, like C-reactive protein and procalcitonin, it predicts severe sepsis in the early stages." (PMID 31877138, 2019). "Biomarkers like procalcitonin, presepsin, CRP all played some role in sepsis mortality prediction, but the reported AUC of ROC curve varies from different settings or sepsis definition." (PMID 31703390, 2019). "Sepsis returned within a few days, however, and the CRP rose to 267 mg/L, with day 22 and 27 blood cultures again growing P. aeruginosa, leading to recommencement of colistin and gentamicin." (PMID 30418554, 2019). "Future studies should aim to develop novel and more accurate methods to improve sepsis diagnosis, such as early molecular detection of bacteria in the blood or monitoring of blood biomarkers (e.g., procalcitonin and C-reactive protein)." (PMID 31432283, 2019). "The NLR is as valuable as CRP for assessing the response to empirically initiated antibiotic treatment in sepsis patients." (PMID 31648506, 2019). "As pointed out above, the proposed biomarkers CRP and IL-6 turn out to lack specificity for sepsis, which has long been considered as the prototypical systemic inflammatory condition." (PMID 30769887, 2019). "In critically ill patients with SIRS, sepsis, or bacteremia, suPAR is superior in predicting mortality compared to other frequently used biological markers, including CRP, PCT, and sTREM-1." (PMID 31191644, 2019). "The Food and Drug Administration (FDA) has recently approved Procalcitonin (PCT) and C-reactive protein (CRP) for diagnosing and monitoring sepsis in the clinical domain." (PMID 33117982, 2019). "After initial signs of sepsis, the patient’s condition improved with the decrease of the fever and the C-Reactive Protein (CRP)." (PMID 30743219, 2019). "Ninety-seven patients with culture-proven sepsis were selected and serial monitoring of CRP and other parameters were studied." (PMID 31065202, 2019). "It was demonstrated that high concentrations of CRP in the development of sepsis indicate unfavorable prognosis." (PMID 31057785, 2019). "IL-6 alone or in combination with other inflammatory markers such as procalcitonin, C-reactive protein, and IL-10 has been shown to identify patients with sepsis in both children and neonates." (PMID 31681719, 2019). "On the other hand, infants with sepsis who had CRP elevation, as well as altered level of consciousness, and seizures, should raise a suspicion for meningitis." (PMID 31537886, 2019). "In this work, we demonstrate a robust, dual marker, biosensing strategy for specific and sensitive electrochemical response of Procalcitonin and C-reactive protein in complex body fluids such as human serum and whole blood for the detection of sepsis." (PMID 33117982, 2019). "Significantly higher values of NLR and CRP were observed in patients with sepsis and septic shock in the ICU." (PMID 31648506, 2019). "Serial monitoring of CRP especially during the first 5 days of initiation of antibiotics in patients with sepsis helps in ascertaining the prognosis and predicting the possible outcome by even the third day of hospitalization." (PMID 31065202, 2019). "No exceptional data was observed among late arrival group (>24 h) as WBC, CRP, and neutrophil count showed to be most sensitive biomarkers in sepsis/bacteremia group." (PMID 30974881, 2019).
Sepsis (continued). "Presepsin showed higher sensitivity and accuracy but relatively lower specificity for the diagnosis of pediatric sepsis than either PCT or CRP." (PMID 31470804, 2019). "During inflammation and sepsis, plasma C-reactive protein (CRP), IL-6, IL-1β, and TNF-α levels in the circulatory system are increased." (PMID 31835381, 2019). "Oconnor E, Venkatesh B, Mashongonyika C, Lipman J, Hall J, Thomas P: Serum procalcitonin and C-reactive protein as markers of sepsis and outcome in patients with neurotrauma and subarachnoid haemorrhage." (PMID 31243609, 2019). "Serum PCT and whole blood PCT were superior to CRP and were similar to serum lactate in predicting bacteremia and 28-day mortality in sepsis." (PMID 31212806, 2019). "The DOR was 53, indicating that neutrophil CD64 determination was a useful tool for diagnosing infection in patients with septic syndrome, based on sepsis-2 criteria, with a performance superior to that of CRP and PCT." (PMID 30623257, 2019). "In summary, we have devised a unique strategy using favorable intrinsic properties of ZnO electrode interface in conjunction with frequency optimization through EIS for the detection of PCT and CRP in human serum and whole blood for early detection of sepsis." (PMID 33117982, 2019). "Those clusters constituted profiles of patients presenting a similar pattern of routinely measured parameters at the peak level of C-reactive protein in sepsis." (PMID 31275752, 2019). "Procalcitonin (PCT) and C-reactive protein (CRP) are acute phase proteins that have been evaluated for use in the diagnosis and prognosis of sepsis and have been included in the diagnostic criteria for sepsis by the Surviving Sepsis Campaign." (PMID 31583025, 2019). "Regarding all the clinicopathological features in sepsis patients, miR-495 expression was negatively associated with Scr, WBC, CRP, PCT, APACHE II score and SOFA score (all P < 0.05)." (PMID 31771650, 2019). "The AUROC to detect sepsis was highest for CRP level with an AUROC of 0.89 (95% CI 0.87–0.92) and PCT level with an AUROC of 0.88 (95% CI 0.86–0.91)." (PMID 30811475, 2019). "On average, these had approximately twofold higher WBCs than presurgical patients, and SOFA scores were around twofold and CRP concentrations around fourfold higher in sepsis compared to SIRS." (PMID 31075840, 2019). "Regarding inflammation, lnc‐THRIL was positively associated with CRP, PCT, TNF‐α, and IL‐1β levels in sepsis patients." (PMID 31257645, 2019). "In patients with sepsis, CRP is a more useful tool in predicting improvement and outcome when compared to scoring systems like SOFA score." (PMID 31065202, 2019). "Although C-reactive protein (CRP) has been proposed as a marker for sepsis, its specificity for this condition is actually low." (PMID 30769887, 2019). "CRP was significantly higher in those patients who had surgery, specifically in those whose sepsis was the indication for surgery." (PMID 31095593, 2019). "Research about the diagnostic ability of CRP and PCT has been conducted in sepsis, but data on the early prognostic value of CRP and PCT are lacking." (PMID 31036824, 2019). "C-reactive protein (CRP) and procalcitonin (PCT) have been widely used to facilitate sepsis diagnosis, but their diagnostic and prognostic values are limited." (PMID 31718563, 2019). "Procalcitonin (PCT) and C reactive protein (CRP) are inflammatory blood markers that have been proven useful to support diagnosis and monitoring of (bacterial) respiratory tract infections and sepsis." (PMID 31401614, 2019). "The results indicate that the value of CRP for the diagnosis of sepsis patients is a moderate degree." (PMID 31671729, 2019). "Consecutive studies concentrated on the strength and diagnostic value of presepsin compared with the most widely used sepsis markers such as CRP and procalcitonin." (PMID 31387523, 2019).
Sepsis (continued). "If there is worsening of CRP, measures can be taken either to rethink on the antibiotics initiated or carry out some intervention to treat the sepsis; for example, incision and drainage for an abscess." (PMID 31065202, 2019). "In line, CTRP3 plasma concentrations were inversely correlated with inflammatory cytokines and standard markers of sepsis such as CRP and PCT." (PMID 31569348, 2019). "In the present study, AGP and CRP levels were significantly correlated in patients with sepsis upon admission, and this observation was similar to that reported in previous studies." (PMID 31309103, 2019). "Cytokines, and in particular IL-6, rapidly increase during severe systemic inflammation, but its specificity for sepsis as a single biomarker, just like for CRP, turns out to be low." (PMID 30769887, 2019). "For patients with sepsis, BMPER concentrations were increased and associated with CRP, PCT, LAC, and SOFA." (PMID 30800678, 2019). "In most studies, PCT has been reported to be superior to CRP for differentiating between sepsis and SIRS." (PMID 31691767, 2019). "As is well known, PCT and CRP are suitable markers for the diagnosis of sepsis, and they have been used for the early detection of infection and guiding of antibiotics therapy." (PMID 31036824, 2019). "Considering these findings and the importance of the early assessment of the clinical course of sepsis, the prognostic value of sTREM-1 compared with CRP, PCT and IL-6 was analyzed in the present study." (PMID 29282483, 2018). "The concentrations of IL-6 (100.45 ± 21.06 pg/mL), PCT (5.38 ± 0.58 ng/mL) and CRP (51.65 ± 6.25 ng/mL) were also higher in sepsis patients group." (PMID 30587127, 2018). "CRP positivity rate and leukocytosis don’t differ significantly between both early and late onset sepsis." (PMID 30069260, 2018). "C-reactive protein (CRP) has also been utilized by some as a biomarker to detect the inflammatory response that occurs with sepsis." (PMID 30332466, 2018). "We conducted a retrospective cohort study to evaluate the use of CRP in the diagnosis of late-onset sepsis in VLBW infants." (PMID 29382319, 2018). "Many studies have described an interrelation between an elevated C-reactive protein level and sepsis." (PMID 30446841, 2018). "The acute phase protein CRP has a high sensitivity for detection of early onset sepsis, but its low specificity is a major drawback for its use as a biomarker to stratify the immune status in patients with sepsis." (PMID 30233566, 2018). "From previously published studies CRP was reported to have low sensitivity during the first hours of sepsis." (PMID 30068303, 2018). "The systemic inflammation during sepsis is observed by measuring leukocytes, procalcitonin, C-reactive protein and others." (PMID 30446841, 2018). "It is a more specific marker of microbial infections than C-reactive protein (CRP) and is used in the diagnosis and assessment of therapeutic effect in sepsis and other systemic infections." (PMID 29725488, 2018). "In that study, the cut-off value for the CRP/albumin ratio as predictor of mortality was 5.09 in patients with severe sepsis or septic shock." (PMID 30297655, 2018). "Considering that the patients with sepsis usually had higher values of inflammatory markers such as CRP or procalcitonin, CRP/ALB ratio in these patients would have higher ratio than with other studies including our study." (PMID 29495423, 2018). "Our study showed that serum levels of tenascin-C in patients with sepsis were significantly positively correlated with serum inflammatory factors, CRP, IL-6 and TNF-α." (PMID 30442110, 2018). "C-reactive protein was used only as a surrogate marker in order to identify the most severe period of the sepsis in each child independently of any treatment; the absolute levels of C-reactive protein are secondary for the objective of this study." (PMID 30202654, 2018).